PLB1 (phospholipase B1)
Diseases named in the same sentence as PLB1 in open-access papers:
PLB1 is named in the same sentence as 37 diseases in open-access papers, as found by Europe PMC text mining. Sharing a sentence is not in itself a finding about the gene and the disease. The quoted sentences say what the papers report.
cryptococcosis (4 papers, 2014 to 2025). An acute or chronic, localized or disseminated infection by Cryptococcus neoformans. "In the lungs, PLB1 promotes eicosanoid production during cryptococcal infection, which is associated with decreased inflammation, a plausible explanation to the significant difference observed in microglial recruitment in brain tissues infected with H99 and Rec1 7-dpi." (PMID 41169392, 2025). "For example, study has shown that disruption of the phospholipase B1 coding gene PLB1 reduces the virulence of C. neoformans in animal models of cryptococcosis." (PMID 41334525, 2025). "In contrast, i.c.-infected mice with Rec1 unexpectedly demonstrated similar cerebral cryptococcosis progression and mortality as animals infected with the plb1 strain." (PMID 41169392, 2025). "We recently established the importance of PLB1 in establishing cryptococcal infection and modulating the immune response in the CNS using a systemic mouse model of infection." (PMID 41169392, 2025). "Several virulence factors are known to play a major role in the pathogenesis of cryptococcal infections, including the enzyme phospholipase B1 (Plb1)." (PMID 25605772, 2015).
glioblastoma (3 papers, 2023). The most malignant astrocytic tumor (WHO grade IV). "PLB1 mutation was reported to be associated with poor survival in non-small cell lung cancer and glioblastoma multiform." (PMID 36779847, 2023).
diabetes (2 papers, 2025 to 2026). "The PLB1 gene was detected in 87.5% of Candida isolates from women with diabetes and in 95% of isolates from women without diabetes." (PMID 40571928, 2025). "Whereas PLA2G6 is known to be a proinflammatory mediator required for monocyte chemotaxis and potentially contributory to both atherosclerosis and diabetes, the link between both PLAG4B & PLB1 and obesity, diabetes, or cardiovascular diseases is currently unknown." (PMID 41186047, 2026).
non-small cell lung carcinoma (2 papers, 2022 to 2023). A group of at least three distinct histological types of lung cancer, including non-small cell squamous cell carcinoma, adenocarcinoma, and large cell carcinoma. "It was reported mutations of rs117512489 in PLB1 (phospholipase B1) was associated with the prognosis of the patients with non-small cell lung cancer." (PMID 35185876, 2022).
autoimmune disease (1 paper, 2014). A disorder resulting from loss of function or tissue destruction of an organ or multiple organs, arising from humoral or cellular immune responses of the individual to their own tissue constituents. "There exist a few reports suggesting contribution of PLB1 and other phospholipase family genes on human autoimmune disease." (PMID 24520335, 2014).
Autoimmunity (1 paper, 2014). The occurrence of an immune reaction against the organism's own cells or tissues. "Recently, whole-exome sequencing analysis on a pedigree with a dominantly inherited immunodeficiency and autoimmunity identified a causal mutation in a gene related to PLB1, the phospholipase Cγ2 (PLCG2) gene." (PMID 24520335, 2014).
Cn (1 paper, 2023). "In this study, we used a PLB1 mutant (plb1) and its reconstituted strain (Rec1) to assess the importance of this enzyme on Cn brain infection in vivo and in vitro." (PMID 36786559, 2023).
co-infection (1 paper, 2016). "PLB1 gene expression was upregulated in the co-infection group at 24 hours after infection (P = 0.0193), but SAP4 gene expression was upregulated in the co-infection group at both 6 and 24 hours after infection (P = 0.0019, P = 0.0062)." (PMID 27874093, 2016).
Coccidioides infection (1 paper, 2016). "In support of this strategy, a combination of recombinant Pep1, Alm1, and Plb1 in a vaccine formulation provided increased protection against Coccidioides infection compared to each individual protein alone." (PMID 26878023, 2016).
Cognitive impairment (1 paper, 2023). Abnormal cognition is characterized by deficits in thinking, reasoning, or remembering. "H99 and Rec1 infection promoted astrocytosis and astrogliosis compared to plb1 infection, particularly in the cortex and hippocampus, suggesting the importance of PLB1 in the development of cognitive impairment in patients with CME." (PMID 36786559, 2023).
COVID-19 (1 paper, 2021). A disease caused by infection with severe acute respiratory syndrome coronavirus 2. "Interestingly, PLB1 preferentially hydrolyses sn-2 acyl chains, and LPC (12:0/0:0) is upregulated in the COVID-19 signatures in the plasma lipidome." (PMID 34659373, 2021).
dementia (1 paper, 2023). Loss of intellectual abilities interfering with an individual's social and occupational functions. "PLB1 causes extensive brain tissue damage and changes microglia morphology during cryptococcal disease, observations which can have important implications in patients with altered mental status or dementia as these manifestations are related to poorer survival outcomes." (PMID 36786559, 2023). "Since PLB1 alters astroglia responses during Cn infection in the cerebral cortex and hippocampus, future studies must focus on understanding the mechanisms by which glial cells may contribute to dementia in CME patients after PLB1-mediated regulation of arachidonic acid and prostaglandin E2 levels." (PMID 36786559, 2023).
encephalomalacia (1 paper, 2023). Localized atrophy of the brain parenchyma due to aging, hemorrhage, infarct, or inflammation. "In the cerebellum, plb1 showed little GXM release in the white matter or the granular layer surrounding the area of encephalomalacia caused by the cryptococcoma." (PMID 36786559, 2023). "Brain infection by H99 and Rec1 produced encephalomalacia extended through the six laminar layers of the cerebral cortex, analyzed sequentially, whereas the plb1- infected cortex exhibited a small circular area limited to laminar layers III and IV." (PMID 36786559, 2023). "In contrast, plb1-infected brains exhibited a smaller encephalomalacia area restricted to the granular layer of the cerebellum." (PMID 36786559, 2023).
lung carcinoma (1 paper, 2022). "Results of next generation sequencing validated the role of PLB1 as a biomarker for lung cancers." (PMID 35185876, 2022).
meningoencephalitis (1 paper, 2023). Inflammation of the meninges and brain, generally secondary to an infectious cause. "In conclusion, recognizing the importance of PLB1 as a virulence factor in cryptococcal CNS colonization and meningoencephalitis development can help us investigate its potential as a therapeutic target." (PMID 36786559, 2023).
metastasis (1 paper, 2023). The spread or migration of cancer cells from one part of the body (where they first appeared) to another. "For cfDNA with PLB1 mutations, patients were more likely to develop distant lymphatic metastasis than peritoneal metastasis." (PMID 36779847, 2023). "In addition, our results showed that PLB1 mutation was more common in the cfDNA of GC patients with single distant lymphatic metastasis than in patients with peritoneal metastasis, which has not yet been reported yet." (PMID 36779847, 2023).
Myocardial fibrosis (1 paper, 2024). "Of the other genes that had significant association with myocardial fibrosis, LIMS1, TLR3 and PLB1 had heart enhanced interactions." (PMID 38848015, 2024).
neuroblastoma (1 paper, 2025). Neuroblastoma (NB) is the most common solid, extracranial childhood tumor. "Quantification of the adhesion ability of Cn strain H99 (P < 0.0001) and Rec1 (P < 0.0001) cells demonstrated increased adhesion to SH-SY5Y neuroblastoma cells relative to that of plb1." (PMID 41169392, 2025). "We investigated the importance of PLB1 in cryptococcal adhesion to and colonization of human neuroblastoma cell line SH-SY5Y [4′, 6-diamidino-2-phenylindole (DAPI), blue nuclei; β-tubulin, green cell body] using fluorescent microscopy." (PMID 41169392, 2025). "Moreover, plb1 cryptococci showed impaired adhesion to SH-SY5Y neuroblastoma cells and decreased cell CPS fiber (SEM) contact or local cell-derived GXM secretion to a solid surface (ELISA spot)." (PMID 41169392, 2025). "Rec1 cells evinced uneven distribution but similar single or aggregate cell binding to neuroblastoma cells or the glass-bottom surface as observed in wild-type cells, potentially due to impaired PLB1 regulation or PLB1 anchoring to or secretion from the fungal membrane." (PMID 41169392, 2025). "Moreover, Cn adhesion to SH-SY5Y human neuroblastoma cells was weakened in the PLB1-disrupted strain, and in vitro biofilm formation showed reduced metabolic activity and thickness." (PMID 41169392, 2025).
type 1 diabetes (1 paper, 2014). "The PLB1 locus has suggestive evidence as a type 1 diabetes risk locus (P<10−6 for the SNP located 70 kbp upstream of PLB1)." (PMID 24520335, 2014).
infection (14 papers, 2015 to 2025). The state of being infected such as from the introduction of a foreign agent such as serum, vaccine, antigenic substance or organism. "It is evident from our findings that PLB1 causes brain damage and may alter the host immune response to infection, which may have important implications in the neurological and behavioral symptoms of patients with CME." (PMID 36786559, 2023). "In a previous study it was identified that the C. neoformans mutant Δplb1 (that lacks the PLB1 gene coding for phospholipase B1) was deficient in replication and survival in macrophages, a phenotype also observed by a number of studies using different in vitro infection assays." (PMID 30921435, 2019). "In this regard, the activity of PLB1 has been suggested to repress titan cell formation during infection." (PMID 41169392, 2025). "In this study, we investigated the involvement of PLB1 in Cn biofilm-like lesion formation using a recently described stereotaxic i.c. mouse model of infection." (PMID 41169392, 2025). "The transcription of Cox-2, Alox5, Hpgds, and Plb1 was significantly upregulated, indicating that AA metabolism in the liver is markedly activated after infection." (PMID 40463366, 2025). "We investigated how the CNS immunity responds to Cn H99, plb1, or Rec1 infection by measuring cytokine production in brain tissue after 7 days." (PMID 36786559, 2023). "It is likely that CD4+ T cell responses were impaired during infection with Cn H99, plb1, or Rec1 due to the baseline levels of IFN-γ detected in the supernatants of brain homogenates." (PMID 36786559, 2023). "We next aimed to address how regulatory networks of known brain-infection factors, such as Ure1, Cps1, Itr1a, Itr3c, Mpr1, Plb1, Fnx1, and Rub1, are connected to brain-infection-related kinases and TFs identified in this study." (PMID 32251295, 2020). "It would be also important to understand how pLB1+/Tdc2+ VM III neurons regulate female egg-laying behavior in response to infection." (PMID 31661076, 2019). "Three key VFs are important for Cn to establish infection in the lung: Phospholipase B1 (Plb1), laccase, and the polysaccharide capsule." (PMID 30863389, 2019). "Consistently, providing ectopic TβH in pLB1+ neurons was shown to rescue egg-laying drop post infection." (PMID 31661076, 2019). "PLB1 knockout leads to a reduced fungal lung burden during murine infection; in addition, it abrogates dissemination to the brain and has previously been shown to reduce budding of C. neoformans within macrophages." (PMID 25605772, 2015). "Furthermore, deletion of the PLB1 gene has demonstrated reduced virulence and proliferation in mouse infection models." (PMID 41169392, 2025). "Further investigation is needed to discern whether the reduction in cryptococcoma formation by plb1 and Rec1 strains results from reduced virulence or containment of the infection by neuroprotective immune responses." (PMID 41169392, 2025). "We hypothesised that PGE2—or other phospholipase B1 derived eicosanoid species—are produced by C. neoformans during infection and promote macrophage infection." (PMID 30921435, 2019). "It has been described that the extracellular part of PLB1 is required for wild-type virulence of Candida in a mouse model of systemic infection, possibly related to its secretion from the hyphal tip during the infection process." (PMID 26300851, 2015). "Plb1 contributes to C. neoformans cell survival during infection." (PMID 25605772, 2015). "In this study, we sought to explore the role of Plb1 during macrophage infection." (PMID 25605772, 2015). "Taken together, our results indicate that microglial responses are influenced by PLB1 production and the amount of GXM released during infection." (PMID 41169392, 2025).
infection (continued). "It is possible that Rec1 or optimal PLB1 activity is stimulated in circulation or following exposure to serum or immune factors prior to invading the CNS, which may explain the reduced virulence relative to the wild-type H99 strain observed in the i.c. model of infection." (PMID 41169392, 2025). "Cn PLB1 or manipulation of the plb1 gene have important implications in cryptococcoma formation and CPS production/accumulation during infection." (PMID 36786559, 2023). "Furthermore, we identified the phospholipase (PLB1) gene (which is an important gene in maintaining the integrity of the chitinous fungal cell wall as well as providing nutrients that can be utilized as a carbon source for C. neoformans during the course of the infection) in all isolates." (PMID 34983525, 2022). "Interestingly, pLB1+/Tdc2+ neurons that adapt female oviposition rate to their infectious status, are also present in males where they might regulate male-specific OA-dependent behaviors upon infection." (PMID 31661076, 2019). "The current study showed that the expression of PLB1 and SAP4 genes was always detected at 24 hours after infection, confirming a potential role of these genes in enterocyte cell damage." (PMID 27874093, 2016). "In nearly all of the isolates, ALS1, HWP1, SAP4–SAP6, LIP1–LIP10, PLB1, and PLB2 were expressed after infection of the cell line A431, whereas CDR1 was expressed in 20 (51.3%) and ALS3 in 14 (35.8%)." (PMID 28058052, 2016). "Plb1 is secreted from the fungus and is and thought to be required for host cell penetration by deacylating phospholipids and thereby producing metabolites such as GPC at sites of infection." (PMID 38072057, 2024). "PLB1 may be responsible for this neurological disorder, which can persist in patients even after CME has been resolved, especially if the infection occurs in the cortex or hippocampus." (PMID 36786559, 2023). "Surprisingly, plb1 cortical infection shows a low number of microglia and no microglial morphological changes from their ramified baseline near or around the cryptococcomas, which were indistinguishable from those in naive mice." (PMID 36786559, 2023). "Our data indicate that most pLB1+ neurons are not involved in controlling the egg-laying rate in response to infection and that a small fraction of them is octopaminergic." (PMID 31661076, 2019). "Expression of both PLB1 and SAP4 genes was detected 6 and 24 hours after infection in both groups." (PMID 27874093, 2016). "In addition, the fact that the Δsec14-1 strain does not manifest similar cell size increases during in vitro infection (our unpublished data) indicates that intracellular rather than extracellular Plb1 activity regulates the titan cell morphology." (PMID 25605772, 2015).
bacterial infection (1 paper, 2019). "We have previously shown that cells expressing Gal4 in the pLB1 pattern (called pLB1+ cells) regulate egg-laying behavior in response to bacterial infection." (PMID 31661076, 2019). "Our published results demonstrated that peptidoglycan-dependent NF-κB activation in octopaminergic neurons inhibits female egg-laying upon bacterial infection and that over-expressing the OA-producing enzyme Tyramine-β-hydroxylase (TβH) in pLB1+ cells counteracts this phenotype." (PMID 31661076, 2019).
neurological disorder (1 paper, 2023). "Cn PLB1 is not essential to cross the BBB and establish neurological disease in mice." (PMID 36786559, 2023).
tumor (1 paper, 2023). "The sensitivity of the mutation status of cfDNA to predict mutation in tumor samples was highest in FAT4 (88.9%), followed by MACF1 (80%), CDH1 (75%) and PLB1 (75%)." (PMID 36779847, 2023).
PLB1 also shares sentences with these, for which no sentence is quoted: cancer (6 papers); ankylosing spondylitis (1); atherosclerosis (1); bacterial meningitis (1); cardiovascular diseases (1); frontotemporal dementia (1); fungal meningitis (1); gastric cancer (1); Hyperhidrosis (1); Immunodeficiency (1); Lymphatic Metastasis (1); Obesity (1); pituitary tumor (1); rheumatoid arthritis (1).